POFUT1 (protein O-fucosyltransferase 1)
Diseases named in the same sentence as POFUT1 in open-access papers (continued):
Sharing a sentence is not in itself a finding about the gene and the disease.
cancer (continued). "From the viewpoint of glycobiology, it is still necessary to analyze how POFUT1 regulates Notch signaling in cancer cells." (PMID 35335147, 2022). "Some of the amplified genes are rarely over-expressed at the mRNA level, while others, such as ASXL1, KIF3B and POFUT1, are over-expressed in most amplified cancers." (PMID 34577783, 2021). "Overall, the high conservation of at least five residues, among the seven mutated ones in CRC patients, as well as the implication of three of them in other types of cancers suggested functional consequences on POFUT1 activity." (PMID 32486426, 2020). "High levels of POFUT1 expression measured by IHC were more frequent in HRAs compared to LRAs, in HRAs and cancers compared to LRAs and in HRAs and cancers compared to LRAs and normal adjacent colon." (PMID 31411736, 2020). "Overall, these results highlighted an undeniable oncogenic activity of POFUT1 in cancer such as CRC." (PMID 32486426, 2020). "POFUT1 overexpression was observed in many cancers affecting different organs such as the liver, stomach, oral cavity, or breast." (PMID 32486426, 2020). "As O-fucosylation of NOTCH receptor is necessary for its activation, several cancer studies focused on POFUT1 expression." (PMID 30380753, 2018). "On a panel of 28 cancer types available in FireBrowse database, POFUT1 expression is predominantly higher in 22 tumors compared to normal tissues." (PMID 30380753, 2018). "The distinction between cancer stages showed a significant (p < 0.001) increase in POFUT1 expression whatever the stage is, therefore at the first signs of the tumor growth." (PMID 30380753, 2018). "POFUT1 levels positively correlated with myeloid-derived suppressor cells (MDSCs) infiltrating in 15 cancer types, while inversely correlated with natural killer T (NKT) cells presence in 15 cancers (mean R = -0.34, p < 0.05), indicating an association with immunosuppressive microenvironments." (PMID 42122137, 2026). "POFUT1 dysregulation, particularly its overexpression, is frequently seen across many cancer types." (PMID 40773107, 2025). "Further investigations are needed to determine whether POFUT1 acts as a tumor suppressor in additional cancers." (PMID 40773107, 2025). "What molecular mechanisms drive POFUT1 overexpression in different cancers?" (PMID 40773107, 2025). "This supports the conclusion that POFUT1 actively drives cancer cell proliferation." (PMID 40773107, 2025). "Interestingly, in cancer types where Notch functions as a tumor suppressor, such as in muscle-invasive bladder cancer (MIBC), low levels of POFUT1 mRNA are associated with poor survival in MIBC patients after radical cystectomy." (PMID 40286076, 2025). "All these mechanisms could promote, independently or collectively, the overexpression of POFUT1, which in turn activates key signaling pathways, crucial for maintaining cancer cell growth, survival, and metastatic potential." (PMID 40773107, 2025). "Notably, different types of cancers exhibit aberrant expression of Notch-modifying glycosyltransferase genes, such as POFUT1, POGLUT1, or Fng." (PMID 35335147, 2022). "Thus, it has been reported that in various cancers, the expression levels of POFUT1 alter Notch signaling in cancer cells, resulting in altered malignant behavior of cancer cells." (PMID 35335147, 2022). "Cancer-associated genes of the locus include ASXL1, DNMT3B, BCL2L1, TPX2, KIF3B and POFUT1." (PMID 34577783, 2021). "Interestingly, POFUT1 expression was lower in MSI than in MSS cancers on both RNA and protein level, suggesting its specific role for chromosomal instability tumors." (PMID 31411736, 2020). "Therefore, these mutations support previous studies considering POFUT1 as a potential biomarker for CRC and other cancers." (PMID 32486426, 2020). "As the Notch signal is responsible for cell proliferation and apoptosis, POFUT1 may participate in cancer progression." (PMID 30619732, 2018).
cancer (continued). "In addition, PLAGL2 and POFUT1, which are separated by shortest physical sequence distance (<150bp) and exhibit co-expression characteristics in 14 cancer types were used for further analysis." (PMID 29108255, 2017). "The Notch pathway is deregulated in many cancers, and alteration of POFUT1 has been reported in several cancers, but further investigation is needed to assess whether there is deregulation of the Notch pathway associated with mutations that affect O-fucosylation in cancers." (PMID 36265581, 2022). "All these data suggest that POFUT1 could play a significant role in cancer development." (PMID 30380753, 2018). "Five—Using STRING database, we found that it had interactions with several proteins involved in different cancers such as TXNDC9, GXYLT2, POFUT1, XXYLT1, FLNA, and ZC3H12C." (PMID 35140741, 2021). "This, along with the presence of a CpG island in the intergenic region between POFUT1 and PLAGL2, indicates that DNA methylation and histone modifications may influence POFUT1 dysregulation in cancer." (PMID 40773107, 2025). "Meanwhile, POFUT1 and POFUT2 genes, involved in cancer-related pathways, have been screened." (PMID 36583106, 2022). "POFUT1 and NOTCH cross talk had been described in two cancer types." (PMID 30380753, 2018). "A recent study demonstrates the role of POFUT1 in promoting HCC progression and the immunosuppressive tumor microenvironment, as higher POFUT1 protein quantity leads to enhanced production and improved stability of programmed death-ligand 1 (PD-L1) on cancer cells." (PMID 40773107, 2025). "Therefore, we started this study to evaluate POFUT1 expression in CRC and determine its potential value as a novel diagnostic biomarker for this cancer." (PMID 30380753, 2018). "The link between POFUT1 and the PI3K/AKT/mTOR signaling pathway has not been really investigated in cancer." (PMID 40773107, 2025). "Glycosyltransferases that modify Notch receptors, including POFUT1, modify proteins that contain EGF repeats with a consensus sequence for each O-glycosylation, so the effect of POFUT1 on cancer cell behavior is not necessarily mediated by Notch signaling." (PMID 35335147, 2022).
tumor (16 papers, 2011 to 2026). "This high POFUT1 expression was associated with more aggressive tumor characteristics, including larger tumor size, poor cellular differentiation, and vascular invasion, contributing to poor survival and high recurrence rates." (PMID 40773107, 2025). "POFUT1 overexpression is significantly associated with aggressive tumor features, including advanced T classifications, higher N classifications, and alteration of cellular differentiation." (PMID 40773107, 2025). "POFUT1 expression is significantly associated with tumor issue site (p = 0.0001), overexpressed in 68.9% of colon and 84.6% of rectum tissues." (PMID 30380753, 2018). "Combined POFUT1/NOTCH1 expressions were significantly associated with tumor issue site (p = 0.00004), pathologic stage (p = 0.00498) and histological type (p < 0.001)." (PMID 30380753, 2018). "In gliomas, particularly low-grade ones (LGG), high POFUT1 expression correlates with poor patient prognosis and increased infiltration of immune-suppressive cells, notably M2-like tumor-associated macrophages (TAMs), regulatory T cells (Tregs), and resting memory CD4 + T cells." (PMID 40773107, 2025). "Similarly, in NSCLC, elevated plasma POFUT1 mRNA levels strongly correlate with tumor progression, offering notable diagnostic performance, with high sensitivity (81.76%) and specificity (86.26%)." (PMID 40773107, 2025). "The differential expression of POFUT1 is associated with tumor sites and pathologic stages of CRC." (PMID 40773107, 2025). "In vivo studies, using subcutaneous xenograft models in nude mice, confirm the role of POFUT1 in tumor promotion through Notch signaling activation." (PMID 40773107, 2025). "Recent studies have highlighted the role of POFUT1 in modulating the tumor microenvironment, particularly through its effect on immune evasion." (PMID 40773107, 2025). "Pooled loss-of-function screens targeting metabolic genes identified nutrient signaling pathways, including Slc7a1, Slc38a2, and Pofut1, as critical determinants of CD8+ T cell fate, with Pofut1 deficiency enhancing memory responses in tumor and viral models." (PMID 40957982, 2025). "This copy number variations (CNVs) in CRC results in elevated POFUT1 expression in tumors compared to non-tumor adjacent tissues." (PMID 40286076, 2025). "Consistent in vitro and in vivo results show that POFUT1 overexpression promotes tumor growth and metastasis, while its knockdown reduces cell proliferation and migration and increases apoptosis." (PMID 40773107, 2025). "By increasing PD-L1 levels, POFUT1 suppresses the infiltration and activity of anti-tumor immune cells, such as CD8 + T cells, thereby fostering an immunosuppressive microenvironment." (PMID 40773107, 2025). "In contrast, when POFUT1 was silenced, a marked reduction in cell proliferation was observed, suggesting a strong link between POFUT1 expression and tumor cell growth." (PMID 40773107, 2025). "The downregulation of the POFUT1 gene associated with a reduced amount of the corresponding protein in MIBC can be linked to the inactivation of the Notch signaling pathway, a known tumor-suppressor mechanism in bladder cancer." (PMID 40773107, 2025). "The identification of these proteins would be helpful to provide more insights into the contribution of POFUT1 to the tumor process." (PMID 32486426, 2020). "POFUT1 expression is significantly higher in 459 (72.8%) tumor compared to normal tissues (p < 0.001)." (PMID 30380753, 2018). "The potential of POFUT1 inhibition as a novel drug target to impede CRC tumor progression, now warrants further investigation." (PMID 30250219, 2018). "The combination of these data implicate POFUT1 as a crucial CRC oncogene, the overexpression of which is intrinsically linked to CRC tumor development." (PMID 30250219, 2018).
tumor (continued). "Despite a low quality of protein migration due to the Optimal Cutting Temperature (OCT) embedded colorectal tissues, we observed an increase (1.134 and 1.565 fold) of POFUT1 labeling in tumor samples compared to normal tissues." (PMID 30380753, 2018). "More recently, POFUT1 overexpression was also detected in oral squamous cell carcinoma and correlated with an increase of tumor size." (PMID 30380753, 2018). "We further demonstrate that POFUT1 silencing dramatically suppresses CRC tumor growth and transplantation in vivo." (PMID 30250219, 2018). "POFUT1, NOTCH1 and POFUT1/NOTCH1 high expressions are significantly associated with the tumor issue site, preferentially overexpressed in rectum tissue (84.6%, 84%, 76.1%, respectively)." (PMID 30380753, 2018). "We confirmed the importance of POFUT1 to promote CRC tumor formation in vivo using mouse models of CRC development." (PMID 30250219, 2018). "As expected, the COADREAD data, which are a compilation of COAD and READ, showed an increased POFUT1 expression in tumor compared to healthy tissues." (PMID 30380753, 2018). "POFUT1 immunolabeling performed on tumors representing each CRC pathological stage confirms that POFUT1 is overexpressed in tumor." (PMID 30380753, 2018). "Overexpression of POFUT1 is also observed in glioblastoma, gastric cancer, oral cancer, and breast cancer, correlating with increased Notch activity and aggressive phenotypes, such as increased cell proliferation, invasion, metastasis, or larger tumor size." (PMID 40286076, 2025). "POFUT1 also plays a crucial role in inhibiting apoptosis, thus promoting tumor cell survival." (PMID 40773107, 2025). "In less frequent CRC cases with no chromosomal amplification and POFUT1 overexpression, gain-of-function mutations in POFUT1 have been identified, potentially contributing to tumor progression." (PMID 40286076, 2025). "How does POFUT1 enhance tumor progression, affecting different oncogenic pathways?" (PMID 40773107, 2025). "Additionally, POFUT1 promotes an immunosuppressive tumor microenvironment that contributes to treatment resistance by immune checkpoint inhibitors." (PMID 40773107, 2025). "This may be because POFUT1 silencing inhibits Notch signal activation, resulting in reduced expression of HES1 and HEY1, which indicated that POFUT1 acts as a tumor promoter in GBM by enhancing the activation of Notch signaling." (PMID 35335147, 2022). "Nevertheless, it is important to note that in the majority of CRC cases analyzed in the present study, both POFUT1 and NOTCH1 are overexpressed (60.5%), suggesting that overexpression of POFUT1 is necessary to ensure O-fucosylation of additional NOTCH receptors in the tumor." (PMID 30380753, 2018). "The data showed POFUT1 promotes CRC tumor growth in vivo as tumor size (188.146 ± 78.359 mm3) and mice weight (1.365 ± 0.765) were significantly lower in SW620-PO-Lv1 cells compared to SW620-NC controls (size = 1024.508 ± 124.930 mm3, weight = 4.109 g ± 0.1986 g)." (PMID 30250219, 2018). "However, in salivary adenoid cystic carcinoma (SACC) where around 81% of SACC patient samples have a high POFUT1 expression, it is associated with a higher T classification of tumor size, but not with lymph nodes, distant metastasis, or overall clinical staging." (PMID 40773107, 2025). "Recently, an increased amount of WT POFUT1, resulting from a chromosomal amplification of the region 20q11.21, was shown in CRC and correlated to tumor progression through NOTCH signaling activation." (PMID 32486426, 2020). "Taken together, our findings demonstrate that POFUT1 is a tumor activating gene during CRC development, which positively regulates CRC tumor progression through activating Notch1." (PMID 30250219, 2018). "In this study, we investigated the role of POFUT1 during CRC development and its contribution to tumor growth and metastasis." (PMID 30250219, 2018).
tumor (continued). "Through wound-healing assays, we evaluated the biological effects of POFUT1 on CRC cell migratory behavior; a vital change of CRC metastasis and tumor progression." (PMID 30250219, 2018). "ShRNA-mediated knockdown of POFUT1 downregulates NOTCH1 signaling, leading to decreased cell proliferation, migration, and induced apoptosis in CRC cells in vitro, as well as suppression of CRC tumor growth and transplantation in vivo." (PMID 40286076, 2025). "In CRC, POFUT1 silencing inhibited cell proliferation, decreased cell invasion and migration, arrested cell cycle progression, and stimulated CRC cell apoptosis in vitro and suppressed CRC tumor growth and transplantation in vivo." (PMID 35335147, 2022). "In breast cancer, overexpression of POFUT1 and activated NOTCH1 signaling was associated with lymph node metastasis and advanced tumor stage, leading to a poor prognosis." (PMID 35335147, 2022). "POFUT1 labeling on CRC biopsies confirmed the overexpression in tumor compared to the adjacent non-tumor tissues." (PMID 30380753, 2018). "Additionally, COSMIC have identified that POFUT1 overexpression mainly occurred in CRC tissues and ranked first in all human tumor tissues, and POFUT1 belonged to the top 20 genes (ranked 5) with extremely high frequency of overexpression in CRC." (PMID 30250219, 2018). "Surprisingly, significant positive correlations between the expressions of POFUT1 and HES1 or HEY1 are found for healthy tissues and not for tumor ones." (PMID 30380753, 2018).
POFUT1 also shares sentences with these, for which no sentence is quoted: oral squamous cell carcinoma (2 papers); acute lymphoblastic leukemia (1); acute myeloid leukemia (1); Adams-Oliver syndrome (1); breast invasive carcinoma (1); cervical cancer (1); colon (1); colon adenocarcinoma (1); Dent Disease 2 (1); endometrial cancer (1); ependymoma (1); esophageal cancer (1); Infertility (1); Keratitis-Ichthyosis-Deafness syndrome (1); lung adenocarcinoma (1); mastitis (1); melanoma (1); myeloma (1); pachyonychia congenita (1); rectal mucinous adenocarcinoma (1); rectum adenocarcinoma (1); Splenomegaly (1); spondylocostal dysostosis (1); T-cell acute lymphoblastic leukemia (1); uterine cancer (1).